MIR4751 (microRNA 4751)
Synonyms: hsa-mir-4751
Gene: MicroRNA gene on chromosome 19 (49,933,064 to 49,933,137, forward strand). Ensembl gene ENSG00000283842.
Homologues: Orthologues: chimpanzee MIR4751 (100% identical).